KLF10 (KLF transcription factor 10)
Description:
Transcriptional repressor which binds to the consensus sequence 5'-GGTGTG-3'. Plays a role in the regulation of the circadian clock; binds to the GC box sequence in the promoter of the core clock component ARTNL/BMAL1 and represses its transcriptional activity. Regulates the circadian expression of genes involved in lipogenesis, gluconeogenesis, and glycolysis in the liver. Represses the expression of PCK2, a rate-limiting step enzyme of gluconeogenesis (By similarity). May play a role in the cell cycle regulation.
Synonyms: TIEG; TIEG1; EGRA; EGR-alpha
Tractability: PROTAC: UniProt records ubiquitination sites on it; ubiquitination databases record sites on it; a small molecule that binds it is known.
Target class: Transcription factor
Gene: Protein-coding gene on chromosome 8 (102,648,783 to 102,655,728, reverse strand). Ensembl gene ENSG00000155090.
Subcellular location: Nucleus
Gene Ontology:
Molecular function: DNA-binding transcription activator activity, RNA polymerase II-specific; protein binding; RNA polymerase II cis-regulatory region sequence-specific DNA binding; sequence-specific double-stranded DNA binding; core promoter sequence-specific DNA binding; DNA-binding transcription factor activity; DNA-binding transcription factor activity, RNA polymerase II-specific
Biological process: positive regulation of transcription by RNA polymerase II; cell-cell signaling; cellular response to starvation; negative regulation of cell population proliferation; negative regulation of DNA-templated transcription; negative regulation of transcription by RNA polymerase II; regulation of circadian rhythm; regulation of transcription by RNA polymerase II; circadian rhythm
Cellular component: chromatin; nucleus
Genetic constraint (gnomAD): Loss-of-function variants: 17 observed, 31.22 expected, observed/expected ratio (o/e) 0.54, 90% interval 0.37 to 0.82. The upper end of that interval is the gene's LOEUF score, 0.82, which puts it in group 3 of 6, group 1 being the genes least tolerant of losing a copy. Missense variants: 518 observed, 614.5 expected, observed/expected ratio (o/e) 0.84, 90% interval 0.78 to 0.91. Synonymous variants: 239 observed, 224.23 expected, observed/expected ratio (o/e) 1.07, 90% interval 0.96 to 1.19.
Gene-disease validity (ClinGen):
ClinGen rates the evidence that KLF10 causes each of these diseases.
hypertrophic cardiomyopathy (autosomal dominant): Limited. A condition in which the myocardium is hypertrophied without an obvious cause.
Homologues: Orthologues: chimpanzee KLF10 (99% identical), macaque KLF10 (98% identical), pig KLF10 (93% identical), rabbit KLF10 (91% identical), mouse Klf10 (85% identical), rat Klf10 (84% identical), guinea pig KLF10 (74% identical), tropical clawed frog klf10 (50% identical). Paralogues in human: KLF11 (36% identical), SP8 (21% identical), SP5 (19% identical), SP7 (19% identical), KLF13 (19% identical), SP9 (19% identical), KLF5 (18% identical), KLF12 (18% identical), KLF14 (17% identical), KLF16 (17% identical), KLF4 (17% identical), KLF2 (17% identical), and 10 more.
Diseases named in the same sentence as KLF10 in open-access papers:
KLF10 is named in the same sentence as 104 diseases in open-access papers, as found by Europe PMC text mining. Sharing a sentence is not in itself a finding about the gene and the disease. The quoted sentences say what the papers report.
pancreatic cancer (16 papers, 2014 to 2024). "In KLF10-deficient pancreatic cancer cells with low SIRT6 levels, LA elevated SIRT6 expression and activity, which led to upregulated glycolytic enzymes." (PMID 34702956, 2021). "KLF10 deficiency correlated with increased migration and distant metastasis of pancreatic cancer cells." (PMID 34702956, 2021). "KLF10 deficiency in pancreatic cancer is linked to accelerated cancer progression and metastasis, but the underlying mechanisms are unclear." (PMID 34702956, 2021). "Pancreatic tumor tissues from KC mice revealed a loss of KLF10 immunolabeling and elevated PKM2 and PDK1 expression." (PMID 34702956, 2021). "KLF10 expression is inversely associated with pancreatic cancer and therefore, KLF10 can be used as a predictive indicator for pancreatic cancer stages." (PMID 29799499, 2018). "The loss of KLF10 expression is correlated with pancreatic cancer stages." (PMID 35743973, 2022). "Furthermore, others found Klf10 silencing correlates with radiation resistance in pancreatic cancer by up-regulator UVRAG (UV radiation resistance-associated gene)." (PMID 31480737, 2019). "The recent association of low expression levels of KLF10 with advanced disease in pancreatic cancer, may in part be explained by the repressive action of KLF10 on EGFR expression." (PMID 24429391, 2014). "Based on previous studies, it is generally accepted that KLF10 is a tumor suppressor in a variety of cancers, such as pancreatic cancer, gastric cancer, and melanoma." (PMID 38523597, 2024). "In the TGFβ-sensitive pancreatic cancer cell line, KLF10 levels were induced by TGFβ treatment and resulted in cell apoptosis." (PMID 37239940, 2023). "KLF10 can suppress lung and pancreatic cancer EMT and invasion by recruiting HDAC1 to suppress the SNAI2 promoter for the removal of histone acetylation (H3K9ac and H3K27ac)." (PMID 37958386, 2023). "The decrease in KLF10 leads to enhanced proliferation, migration, and invasion of pancreatic cancer." (PMID 37239940, 2023). "Deletion of KLF10 in pancreatic cancer led to downregulation of glucose uptake, lactate production, and glycolytic activity and reduction in mitochondrial oxidative phosphorylation, basal respiration, and maximal respiration capacity." (PMID 37239940, 2023). "The same study demonstrated that KLF10 can regulate radiosensitivity of pancreatic cancer cells by modulating autophagy." (PMID 37239940, 2023). "In this study, we found that additional deletion of KLF10 in the murine model of spontaneous pancreatic cancer accelerated PDAC tumorigenesis." (PMID 37308977, 2023). "Multiple logistic regression analysis also revealed that KLF10 is an independent prognostic factor of prognosis-free survival and overall survival in pancreatic cancer." (PMID 35743973, 2022). "In TGF-beta-resistant pancreatic cancer cells, the ectopic expression of KLF10 increases chemosensitivity to gemcitabine and induces apoptosis." (PMID 35743973, 2022). "Recent studies, including ours, have revealed the downregulation of KLF10 in several advanced cancers, including breast, lung, and pancreas cancers, which results in the development of cancer metastasis." (PMID 34702956, 2021). "From the pancreatic tumor specimens of 105 patients who received curative intent surgery, 66 (62.9%) patients presented a low expression of KLF10, according to the definition described in the “Materials and methods” section." (PMID 34702956, 2021). "Reduced expression of a tumor suppressor gene called Krüppel-like factor 10 (KLF10) is found in breast, lung and pancreatic cancers." (PMID 34702956, 2021). "Several studies have broadly analyzed the probable mechanism and distinct importance of KLF10 in numerous types of cancer, such as pancreatic cancer, renal cell carcinoma, breast cancer, etc.." (PMID 33379261, 2020).
pancreatic cancer (continued). "One previous study aimed to identify the clinical prognostic role of KLF10 in pancreatic cancer, and a higher expression of KLF10 was shown to be an independent predictor of progression-free survival and overall survival for pancreatic cancer patients." (PMID 33379261, 2020). "KLF10 demonstrate anti-proliferative effects and induce apoptosis in various carcinoma cells including pancreatic cancer, leukemia, and osteoporosis." (PMID 29799499, 2018). "The expression of KLF10 is inversely correlated with pancreatic cancer stage, prognosis and overall survival." (PMID 28056099, 2017). "Reduced expression of KLF10, as reported for breast and pancreatic cancer, can promote invasive and metastatic behaviour by enhancing EGFR expression." (PMID 24429391, 2014). "In addition, IHC revealed prominent ductal dysplasia, tumor invasion, and fibrotic stroma with down-regulated KLF10 expression in the majority of the pancreatic tumors of KKC mice." (PMID 37308977, 2023). "Another study showed that KLF10 levels in pancreatic cancer can be regulated by degradation." (PMID 37239940, 2023). "The expression of KLF10 was negatively correlated with the progressive worsening of pancreatic cancer; therefore, KLF10 may be used as a predictor of pancreatic cancer staging." (PMID 36755291, 2023). "To evaluate the role of KLF10 in pancreatic cancer metastasis, we established stable clones of Panc-1 and ASPC-1 cells with KLF10 mRNA silencing (Panc-1shKLF10, and ASPC-1shKLF10) and MiaPaCa cells with inducible KLF10 overexpression given their inherent expression of KLF10." (PMID 34702956, 2021). "KLF10 is located on chromosome 8q22, where mutations are quite frequent in pancreatic cancers; however, mutational screening of a panel of the twenty-two human pancreatic cell lines showed no alteration in KLF10 expression." (PMID 29799499, 2018). "In agreement, KLF10 protein expression correlated inversely with disease stage in a collection of 95 tissue samples of pancreatic adenocarcinoma and independently predicted progression-free and overall survival in pancreatic cancer." (PMID 24429391, 2014). "However, no alterations in KLF10 expression were found in a mutation screening study of 22 human pancreatic cancer cell lines." (PMID 37958386, 2023). "In contrast to most studies, KLF10, a transcriptional repressor, was found to transcriptionally activate SIRT6 in pancreatic cancer cells." (PMID 34702956, 2021). "Metformin can induce KLF10 expression via AMPK and increase the radiosensitivity of pancreatic cancer cells." (PMID 33485367, 2021). "KLF10 mimics TGF-β action and plays a role in the development of human osteosarcoma 13, pancreatic carcinoma 24, breast cancer 25 and renal cancer." (PMID 32549754, 2020). "Krüppel-like factor 10 (KLF10) is a well-known tumor suppressor of KLFs family because of its inhibitory effect on cell proliferation, and has become a research target for lung cancer, pancreatic cancer and liver cancer, which is first discovered as TGFβ inducible early gene 1 in osteoblasts." (PMID 36878898, 2023).
breast carcinoma (13 papers, 2009 to 2026). "KLF10 has been indicated as a marker for breast cancer, and different stages of breast tumor tissues from different populations show decreased mRNA levels of KLF10, Smad2, and BRAD1 (breast cancer 1 associated RING domain 1), while Smad7 is inversely correlated with KLF10." (PMID 29799499, 2018). "In vivo experiments confirmed that KLF10 promoted breast cancer metastasis, with its expression positively correlated with p65 and negatively correlated with IκBα." (PMID 41797918, 2026). "Stage-specific expression of KLF10 in breast cancer biopsies has been published, with sustained downregulation leading to complete absence of expression in invasive subtypes." (PMID 41048341, 2025). "KLF10 can inhibit breast cancer invasion and metastasis by inhibiting epidermal growth factor receptor (EGFR) transcription and the EGFR signaling pathway." (PMID 28056099, 2017). "Here, we showed that KLF10 promoted breast cancer progression by activating the NF-κB cascade." (PMID 41797918, 2026). "KLF10 and its target genes play important roles in breast cancer." (PMID 29799499, 2018). "KLF10 is an anti-metastasis gene that significantly prevents breast cancer cell invasion, suppresses mammary tumorigenesis and decreases lung metastasis by inhibition of EGFR (epidermal growth factor receptor) gene transcription through the EGFR signaling pathway." (PMID 29799499, 2018). "Expression levels of BDNF and BDNF-correlated genes CCND2, DUSP6, EGR1, KLF10 and PTPRF are altered in breast cancer." (PMID 19737418, 2009).
multiple myeloma (13 papers, 2017 to 2024). "KLF10 loss activates PTEN/PI3K/AKT activity in multiple myeloma and bladder cancer." (PMID 37958386, 2023). "The biological effects of miR-410 on multiple myeloma cells were at least partially eliminated by altering KLF10 expression or using an AKT inhibitor." (PMID 38338876, 2024). "Knock-down of securin, the downstream target of KLF10, can mimic the tumor suppressor role of KLF10 in multiple myeloma." (PMID 37958386, 2023). "KLF10 overexpression can suppress Wnt signaling and GSK3β phosphorylation to inhibit the proliferation, migration, and drug resistance of multiple myeloma cells." (PMID 37958386, 2023). "KLF10 inhibits β-catenin nuclear transformation and Wnt signaling pathways in vivo, supporting its potential therapeutic target of multiple myeloma." (PMID 36755291, 2023). "OIP5‐AS1 suppression facilitates cell proliferation and inhibits apoptosis by directly targeting KLF10 via activating the PTEN/PI3K/AKT pathway in myeloma cells." (PMID 36057947, 2023). "Under the regulation of miR-106b-5p, KLF10 functions as a tumor suppressor in multiple myeloma by inhibiting β-catenin nuclear translocation." (PMID 36761967, 2023). "Downregulation of KLF10 was found in multiple myeloma tissues compared to normal groups, whereas overexpression of KLF10 mitigated the proliferation of multiple myeloma cells by controlling PTTG1 expression." (PMID 35743973, 2022). "OIP5-AS1 loss causes miR-410 accumulation that facilitates cell cycle progression, proliferation and apoptosis inhibition by targeting Krüppel-Like Factor-10 (KLF10) via activating the PI3K/AKT/mTOR pathway in multiple myeloma." (PMID 33801659, 2021). "KLF10 inhibits cancer by blocking cell cycle progression in multiple myeloma." (PMID 36761967, 2023). "KLF10 is significantly diminished in multiple myeloma relative to in normal tissues." (PMID 35743973, 2022). "It has been reported that in multiple myeloma cells, miR-410 is negatively modulated by lncRNA OIP5-AS1 that prevents its repression of its target Kruppel-Like factor 10 (KLF10)." (PMID 38201476, 2023). "KLF10 attenuates the nuclear translocation of beta-catenin, inhibits the expression of PTTG1, and then decreases the proliferation of multiple myeloma." (PMID 35743973, 2022). "However, the role of KLF10 in multiply myeloma (MM) development and progression remains unknown." (PMID 32549754, 2020).
diabetes (11 papers, 2013 to 2026). "Mutations in the klf-11 locus are associated with risk of diabetes, while Klf-10 appears to negatively regulate lipogenic genes in hepatocytes." (PMID 23593032, 2013). "This indicated that high expression of KLF10 may be associated with the process of periodontitis of type 2 diabetes mellitus." (PMID 35730406, 2022). "It is noted that the variant of the KLF10 gene contributes to the risk of type-2 diabetes mellitus." (PMID 35730406, 2022). "Collectively, these findings establish the KLF10/GPX4 axis as a previously unrecognized regulator of diabetes-associated vascular ferroptosis and suggest that PTX may offer a promising therapeutic approach for limiting ferroptosis-driven vascular injury in diabetes." (PMID 41926082, 2026). "KLF10 depletion improved diabetes-induced renal fibrosis by downregulating Dickkopf-1 (DKK-1) expression, which was associated with reduced Wnt/β-catenin signaling activity." (PMID 38279278, 2024). "Both KLF10 and KLF11 are closely linked to hepatic gluconeogenesis, hyperglycemia, glucose intolerance, diabetes, and hepatic metabolic disorders." (PMID 39272379, 2024). "KLF10 has the potential to be a marker of various diseases, including cardiac hypertrophy, diabetes, osteoporosis, immune system diseases, and colitis." (PMID 36755291, 2023). "The expression of type IV collagen and fibronectin significantly increased in the diabetes group, whereas knockout of KLF10 repressed diabetes-induced type IV collagen and fibronectin expression." (PMID 35565995, 2022). "Knockout of KLF10 obviously diminished diabetes-induced tumor growth factor-β (TGF-β), fibronectin, and type IV collagen expression, as evidenced by immunohistochemical staining." (PMID 35565995, 2022). "DKK-1 expression was significantly elevated in KLF10 knockout diabetes group compared with KLF10 knockout alone (p < 0.05)." (PMID 35565995, 2022). "No significant alternation of fibronectin and type IV collagen was found in the KLF10 knockout diabetes group compared with the KLF10 knockout alone." (PMID 35565995, 2022). "KLF10 was up-regulated in both patients with periodontitis and type 2 diabetes mellitus with periodontitis." (PMID 35730406, 2022). "In this study, we explored the effects of KLF10 on diabetes-induced renal disease by using a KLF10 knockout mice model." (PMID 35565995, 2022). "While not previously characterized in the inner ear, Klf10 overexpression has been implicated in renal podocyte dysfunction in diabetic nephropathy with suppression of Klf10 shown to reduce diabetes-induced proteinuria and kidney injury in mice." (PMID 34566577, 2021). "Following treatment with STZ, we found that KLF10 depletion significantly protected mice against diabetes‐induced proteinuria (urinary excretion of total protein and albumin), glomerular cell apoptosis, GBM thickening, and even renal fibrosis (and EV3)." (PMID 30948420, 2019). "Inactivation of KDM6A and KLF10 in mice can significantly protect against diabetes‐induced proteinuria and kidney injury." (PMID 30948420, 2019). "This indicated that high expression of KLF10 may be involved in the process of periodontitis of type 2 diabetes mellitus." (PMID 35730406, 2022). "In addition, we found that KLF10 was up-regulated in both patients with periodontitis and type 2 diabetes mellitus with periodontitis." (PMID 35730406, 2022). "Our findings suggest that KLF10 may be a promising therapeutic choice for the treatment of diabetes-induced renal fibrosis." (PMID 35565995, 2022). "Importantly, inactivation or knockout of either KDM6A or KLF10 in mice significantly suppresses diabetes‐induced proteinuria and kidney injury." (PMID 30948420, 2019). "Furthermore, to test whether KLF10 involved in diabetes-induced renal fibrosis, we have performed Masson’s Trichrome staining and positive intensity was determined as previously reported." (PMID 35565995, 2022).
diabetes (continued). "Downregulation of KLF10 diminished the expression of DKK-1 and phosphorylated β-catenin in the diabetes group." (PMID 35565995, 2022). "This study aims to investigate the effects of KLF10 on renal fibrosis-related proteins including TGF-β1 and DKK1 pathway expression in STZ-induced diabetes by using KLF10 knockout mice." (PMID 35565995, 2022). "The expression of diabetes-induced DKK-1 and phosphorylated β-catenin was mitigated in the KLF10 knockout group." (PMID 35565995, 2022). "However, KLF10 mRNA expressions were not significantly correlated with diabetes or dyslipidemia in present study." (PMID 27899146, 2016).